TMPRSS2 (transmembrane serine protease 2)
Diseases named in the same sentence as TMPRSS2 in open-access papers (continued):
Sharing a sentence is not in itself a finding about the gene and the disease.
prostate carcinoma (continued). "Studies have indicated that TMPRSS2:ERG fusion may co-operate with the loss of the tumor suppressor PTEN and the concomitant activation of AKT to promote the progression of prostate cancer from high-grade prostatic intraepithelial neoplasia (PIN) to invasive prostate carcinoma." (PMID 40332527, 2025). "However, it is tempting to speculate that this effect could result from the known interaction between ERG and PRMT5 that can only occur in TMPRSS2:ERG fusion positive prostate cancers." (PMID 40554389, 2025). "Menin may also promote AR-positive prostate cancer growth by promoting JunD and TMPRSS2 expression." (PMID 39336822, 2024). "Firstly, it comprehensively addresses various facets of TMPRSS2 and p300 biology, including their basic biochemical features and physiological functions and their implication in carcinogenesis in general as well as their important role in the molecular pathology of prostate cancer." (PMID 37511059, 2023). "In prostate cancer, reduced PSAP staining was strongly linked to an advanced pT stage, a high classical and quantitative Gleason score, lymph node metastasis, high pre-operative PSA levels, early PSA recurrence (p < 0.0001 each), high androgen receptor expression, and TMPRSS2:ERG fusions." (PMID 37892063, 2023). "The silence of TMPRSS2 could inhibit the proliferation of prostate cancer cells." (PMID 36992839, 2023). "Moreover, inhibition of apoptosis was found in TMPRSS2-ERG-positive prostate cancer cells." (PMID 35017320, 2022). "Additionally, IR treatment caused a marked induction of the androgen target genes TMPRSS2 and FKBP5 in prostate cancer cells, suggesting that DNA damage may directly induce AR activity." (PMID 35954292, 2022). "TMPRSS2 inhibitor could decrease prostate cancer severity in a mouse model." (PMID 34527703, 2021). "TMPRSS2 has been implicated in prostate cancer, not long after its discovery and cloning." (PMID 34001144, 2021). "Additionally, HDAC inhibitors have been shown to repress TMPRSS2-ERG expression in prostate cancer." (PMID 33602138, 2021). "Notably, the prostate gland and prostate cancer cells express Furin; thus, the virus may efficiently enter the prostate gland and/or prostate cancer cells using TMPRSS2 or Furin to initiate or enhance carcinogenesis." (PMID 32974166, 2020). "Elevated expression of TMPRSS2 in the context of SARS-CoV-2 infections implies that SARS-CoV-2 infection could increase chances of TMPRSS2 fusions, a phenomenon well-associated with prostate cancer development and progression." (PMID 32974166, 2020). "An SNP of the TMPRSS2 gene (rs12329760 C>T; Met160Val) present in an exonic splicing enhancer srp40 site, which is highly conserved across mammals, has been found to be associated positively with TMPRSS2–ERG fusion by translocation due to an increased chance of exon skipping in prostate cancer." (PMID 33101356, 2020). "Thus, one may argue that the systemic inflammatory response induced by COVID19 infection could promote gene rearrangements to form TMPRSS2-ERG fusions and increase risk of prostate cancer." (PMID 33076397, 2020). "In favor of the luminal origin is also the recent observation showing that androgen receptor mediates formation of the TMPRSS2-ERG fusion in human prostate cancer cells, thus suggesting that cancer initiating events may occur at the level of androgen receptor-positive luminal cells." (PMID 31366128, 2019). "Interestingly, a TMPRSS2 inhibitor suppressed prostate cancer metastasis." (PMID 31366128, 2019). "The significant up-regulation of ROCK1 in cancers harboring the TMPRSS2:ERG fusion fits with an earlier report describing increased expression of ROCK’s upstream regulator Rho guanine diphosphate dissociation inhibitor beta (ARHGDIB) in ERG positive prostate cancers." (PMID 31557128, 2019). "Therefore, patients with TMPRSS2-ERG-positive prostate cancer could benefit from novel inhibitors targeting the alternative DHT biosynthesis." (PMID 31366128, 2019).
prostate carcinoma (continued). "Hence, the TMPRSS2-ERG fusion gene in prostate cancer could be considered for use as a noninvasive tumor marker for therapy assessment, risk stratification, and relapse detection to improve personalized therapy strategies." (PMID 31915468, 2019). "We detected n = 40 fusion-positive cases (7.7%) with TMPRSS2::ERG in prostate cancer being most prevalent (n = 9/40; 22.5%), followed by other gene fusions identified in cancers of unknown primary (n = 6/40; 15.0%), adenoid cystic carcinoma (n = 7/40; 17.5%), and pancreatic cancer (n = 7/40; 17.5%)." (PMID 31491926, 2019). "In addition, cribriform prostate cancer possesses other unique molecular and genetic features; for example, p63, high molecular weight cytokeratin, and TMPRSS2-ERG gene fusion are reportedly significantly more common in cribriform tumors than non-cribriform tumors." (PMID 28212551, 2017). "Indeed, many androgen-regulated genes have been identified and shown to be important in prostate cancer, including PSA (prostate specific antigen), hKLK2 (human kallikrein-2), TMPRSS2 (transmembrane protease, serine 2), ETV1 (Ets variant gene 1), and sGCα1 (soluble guanylyl cyclase α1)." (PMID 28859127, 2017). "The original prostate cancer study indicated that the 14 prostate cancer samples harbored 38 tumor-specific chimeric transcripts, of which at least 5 are recurrent transcripts in Chinese population, including TMPRSS2-ERG, USP9Y-TTTY15, CTAGE5-KHDRBS3, RAD50-PDLIM4, and SDK1-AMACR." (PMID 29181411, 2017). "Although the clinical significance of TMPRSS2-ERG is yet to be proven, presence of the fusion gene is a key genomic event specific for prostate cancer that may be of importance for risk assessment or treatment stratification of prostate cancer patients." (PMID 27276682, 2016). "From the initial discovery in 2005, the TMPRSS2- ERG gene fusion has been linked to clinical outcome parameters such as early onset of prostate cancer, negative outcome in watchful waiting patients and a higher risk of disease progression in active surveillance patients." (PMID 27276682, 2016). "How the fusion products regulate prostate cancer remains unclear, although it has been observed that an increased incidence of the TMPRSS2:ERG fusion protein in prostate epithelial cells correlates with increased cell invasiveness, poor prognosis and higher rates of malignancy." (PMID 27208692, 2016). "Therefore, siRNA TMPRSS2-ERG-squalene nanoparticles may be a promising alternative therapy for patients with castration resistant prostate cancer." (PMID 25933120, 2015). "Furthermore, advances in classification of many cancer promoting genes and miRNA signatures for uncovering the biological mechanism of oncogenic TMPRSS2-ERG fusions associated genomic changes have been summarized, along with the drug targets and biomarkers for prostate cancer development." (PMID 24739220, 2014). "The identification of recurrent gene fusions in common epithelial cancers—for example, TMPRSS2/ERG in prostate cancer and EML4/ALK in nonsmall cell lung carcinomas —has raised the question of whether fusion genes are pathogenetically important also in ovarian carcinomas." (PMID 24504521, 2014). "The epidermal growth factor (EGF)/Src tyrosine kinase pathway also contributes to the induction of EMT in TMPRSS2:ERG positive prostate cancers, and Kao and colleagues demonstrated that this interaction may be mediated by downregulation of miR-30, which normally suppresses ERG expression." (PMID 25496077, 2014). "In addition, it is noted that different established prostate cancer cell lines may have different statuses for TMPRSS2-ERG." (PMID 24739220, 2014). "Thus, the frequently observed haploinsufficiency of NKX3.1 in prostate cancer may significantly contribute to the activation of ERG protooncogene in the TMPRSS2-ERG fusion genomic context." (PMID 24418414, 2014).
prostate carcinoma (continued). "In addition, the presence of the TMPRSS2:ERG fusion protein could be detected by immunostaining with the rabbit monoclonal anti-ERG antibody in fusion-positive vCaP prostate cancer cells captured by the device and analyzed by multiplex confocal microscopy." (PMID 22558290, 2012). "These prostate cancer-specific gene rearrangements may be explained by the fact that androgen treatment in AR-positive prostate cancer cell lines induced proximity between TMPRSS2 and ERG." (PMID 22110995, 2011). "Recently, recurrent fusions between the transmembrane protease serine 2 (TMPRSS2) gene and members of the ETS family of transcription factors (mainly the v-ets erythroblastosis virus E26 oncogene homolog (avian), ERG, and the ets variant 1, ETV1) were reported in prostate cancer." (PMID 20964841, 2010). "As the TMPRSS2:ERG gene fusion was detected in one out of two Gleason 6 cultures tested, and is associated with lethal prostate cancer, further study of larger samples of prostate cancer stem cells from different classes of therapy-resistant and Gleason 6 tumors is warranted." (PMID 18492237, 2008). "A notable example is the E26 translationally specific (ETS) family of transcription factor fusions in prostate cancer, with the TMPRSS2-ERG fusion being the most prevalent, occurring in approximately 50% of prostate cancer cases." (PMID 40771930, 2025). "TMPRSS2-ERG fusion, found in roughly 100,000 cases every year, is the most common molecular alteration (40-50%) in prostate cancer patients." (PMID 41244516, 2025). "For example, TMPRSS2-ERG and SLC45A3-BRAF fusions in prostate cancer similarly amplify oncogene expression via highly active promoters." (PMID 41422314, 2025). "In summary, AR modulates YAP expression through TMPRSS2-ERG, which has significant implications for the progression of prostate cancer." (PMID 39963114, 2025). "Specifically, we observed racial differences in expression of prostate cancer driver gene pathways (including potential clinically actionable pathways of IFN-γ and JAK/STAT) and DNA alterations, including TMPRSS2:ERG gene fusion." (PMID 40164700, 2025). "Studies have found that in about 50% of prostate cancer cases, intronic deletions between the TMPRSS2 and ERG genes lead to the fusion of the TMPRSS2 promoter with ERG, a fusion that exists in over 90% of ERG-overexpressing prostate cancers." (PMID 39963114, 2025). "Genomic rearrangements involving ETS family genes, predominantly TMPRSS2-ERG fusion, are recurring events in prostate cancer, further shaping its genetic identity." (PMID 40432836, 2025). "Our findings demonstrate the importance of PTEN and TMPRSS2:ERG fusion and tumour molecular subtyping in prostate cancer precision medicine." (PMID 40165885, 2025). "Regarding TCGA patients, TMPRSS2-ERG fusion was detected in 28.6% (140/489) of localized primary prostate cancer out of which 60% (84/140) exhibited both PCP4 deletion and TMPRSS2-ERG fusion." (PMID 40746562, 2025). "TMPRSS2 facilitates SARS-CoV-2 entry into host cells and is simultaneously one of the most frequent genomic drivers in prostate cancer through its fusion with ERG." (PMID 41267989, 2025). "In prostate cancer (PCa), up to 50% of cases are characterized by TMPRSS2:ERG gene fusions, in which ERG expression is driven by the androgen-responsive TMPRSS2 promoter." (PMID 38530366, 2024). "TMPRSS2:ERG gene fusion, which is reported to occur in between 20–80% of prostate cancer, leads to changes promoting EMT, as demonstrated in an in vitro prostate cancer model consisting of immortalised prostate epithelial cells in culture." (PMID 38730670, 2024). "The well‐known AR target genes TMPRSS2 and FKBP5 show enhanced chromatin accessibility, as assessed by ATAC signals, in prostate cancer samples (TCGA‐PRAD)." (PMID 38483933, 2024).
prostate carcinoma (continued). "The potential of various biomarkers such as gene fusions (TMPRSS2-ERG), noncoding RNAs (SNHG12), proteins (PSA, PSMA, AR), and circulating tumor cells (CTCs) in the diagnosis, prognosis, and targeted therapies of prostate cancer is emphasized." (PMID 40353136, 2024). "Studies have shown that the androgen signaling pathway plays a role in facilitating the formation of the TMPRSS2::ERG gene fusion, which is present in approximately 50% of prostate carcinomas." (PMID 39087020, 2024). "Among the new biomarkers is the TMPRSS2-ERG fusion gene, the most common (90% of all genes that fuse with ERG) genetic alteration seen in prostate cancer." (PMID 38730435, 2024). "The TMPRSS2–ERG fusion, a high-frequency fusion gene in prostate cancers, was identified in 34% of the patients." (PMID 38050021, 2023). "Several studies tried to investigate the pathogenetic role of TMPRSS2:ERG fusion in carcinogenesis and the development of prostate cancer." (PMID 37511059, 2023). "The TMPRSS2:ERG fusion, as one of the most common molecular aberrations in prostate cancer, has been extensively studied as a potential therapeutic target." (PMID 37511059, 2023). "Real-time PCR showed a significant induction of PSA, TMPRSS2, and KLK2 mRNA expression with the supplementation of 1 and 10 nM R1881 in LNCaP and VCaP prostate cancer cells." (PMID 37744273, 2023). "A pilot study showed the presence of two known prostate cancer biomarkers, PCA-3 and TMPRSS2: ERG, in exosomes isolated from patients’ urine as a potential diagnosis and monitoring of prostate cancer patient status." (PMID 37456253, 2023). "In prostate cancer, oncogenic alterations in PIK3CA and AR were enriched in TMB and bTMB≥10 samples, whereas TMPRSS2-ERG fusions were more likely to be found in TMB and bTMB<10 samples." (PMID 40027285, 2023). "The fusion of the promoter of TMPRSS2 with the coding region of ERG is the most prevalent molecular aberration in prostate cancer; it occurs in approximately 50% of prostate cancer cases and is the most common gene fusion in solid tumors." (PMID 37511059, 2023). "Similar to prostate cancer cells and derived PDOs, early PCCs and PDOs derived from them expressed cancer markers AMACR, TMPRSS2-ERG, and EZH2." (PMID 36769153, 2023). "Overall, p300 plays a crucial role in mediating chromatin looping, enhancer activation, and co-regulation of TMPRSS2 and PRCAT38 in response to androgen signaling in prostate cancer cells." (PMID 37511059, 2023). "The study highlights the fact that TMPRSS2:ERG fusion transcriptionally upregulates sGC; promoting cGMP synthesis in prostate cancer cells thus enhances cellular proliferation." (PMID 37511059, 2023). "TMPRSS2 induces proinvasive EMT and metastasis in a prostate cancer model, potentially through prohepatocyte growth factor (HGF) activation and subsequent c-MET signaling." (PMID 37009799, 2023). "The over-expression of ERG is highly attributed to the TMPRSS2: ERG fusion, a recurrent chromosomal rearrangement that represents the most common molecular alteration of prostate cancer, approximately occurring in one-half of the cases." (PMID 37185705, 2023). "Integrative clinical data from 18 prostate cancer cohorts and experimental evidence showed that gene fusion between transmembrane serine protease 2 (TMPRSS2) and ETS transcription factor ERG (ERG) (TMPRSS2–ERG fusion) is involved in the silencing of SNAI2." (PMID 34792282, 2022). "These include NanoString detection of two well-established biomarkers for prostate cancer PCA3 and TMPRSS2:ERG." (PMID 35454901, 2022). "In prostate cancer (PCa), ERG is the most overexpressed oncogene in patient tumour samples and the TMPRSS2‐ERG fusion, which can be formed by translocation or interstitial deletion, is a suspected driver of tumourigenesis in about 50% of prostate cancers." (PMID 35472129, 2022).
prostate carcinoma (continued). "TMPRSS2-ERG gene fusion occurs in approximately 50% of prostate cancer (PCa) cases, and the fusion product is a key driver of prostate cancer." (PMID 35281819, 2022). "When comparing prostate cancer patients’ urine exosomes to controls, transcriptome profiling revealed increased levels of PCA-3 (prostate cancer antigen 3 gene) and TMPRSS2-ERG (transmembrane protease serine 2-ETS-related gene)." (PMID 35159299, 2022). "We observed that TMPRSS2 and CXCL10, together with their often co-expressed genes, are important in the binding activity and immune responses in prostate cancer and COVID-19 infection, respectively." (PMID 36239108, 2022). "In search of endogenous inhibitors of TMPRSS2, Ko and coworkers performed co-immunoprecipitation assays on prostate cancer cells and identified HGF activator inhibitor (HAI)-1 and HAI-2 as interaction partners of TMPRSS2." (PMID 35163273, 2022). "FOXA1 is driven by the androgen receptors and regulates the expression of TMPRSS2 and ACE2 in prostate cancer cells." (PMID 35458567, 2022). "The functional importance of TMPRSS2 and CXCL10 in prostate cancer development was then determined by analyzing the frequency of genetic changes in their amino acid sequences using the cBioPortal online portal." (PMID 36239108, 2022). "TMPRSS2-ERG was the only fusion that LINX found to be recurrently chained in the cohort, accounting for 14 of the 43 predicted chained fusions, all in prostate cancers." (PMID 36776527, 2022). "In prostate cancer cells, a surprisingly common occurrence involves the fusion of ERG to TMPRSS2, which forms the fusion product of TMPRSS2-ERG." (PMID 35563163, 2022). "In particular, the most common chromosomal aberration in prostate cancer is the fusion of erythroblast-specific-related gene (ERG) and the 5′-UTR of TMPRSS2." (PMID 35017320, 2022). "For example, the TMPRSS2-ERG, which originates from an interstitial deletion in chromosome 21, has been identified in ∼50% of prostate cancer cases." (PMID 35251131, 2022). "TMPRSS2-ERG rearrangement, the most common ETS gene fusion in prostate cancer, brings ERG expression under androgen control via androgen receptor-mediated TMPRSS2 regulation and results in over-expression of ERG protein." (PMID 35513774, 2022). "Bioinformatic analysis has uncovered various fusions in the 5’ untranslated region of TMPRSS2 (21q22) when it is fused to ERG (21q22), ETV1 (7p21), ETV4 (17q21), or ETV5 (3q27), resulting in the overexpression of ETS and ETS-related genes in prostate cancer." (PMID 35563163, 2022). "In 2005, seminal work by Tomlins and colleagues identified gene fusions between the AR-regulated gene TMPRSS2 and ERG in a large subset of prostate cancer samples." (PMID 35267426, 2022). "The transcriptional promoter for TMPRSS2 is androgen-responsive and was initially described in the context of TMPRSS2-EGR fusion gene and prostate cancer." (PMID 34707243, 2022). "Thus, target inhibition of ERG or TMPRSS2 may be beneficial in prostate cancer." (PMID 35547880, 2022). "Besides eNOS-NO as potential targets, targeting its upstream regulators (ERRα and ERG) of eNOS-NO signaling could also be the therapeutic strategy for the management of advanced prostate cancer, particularly the aggressive cancer carrying with the TMPRSS2:ERG fusion gene." (PMID 35526071, 2022). "Data generation was done representing multiple genetic variations in TMPRSS2 and CXCL10 mRNA using the cBioPortal database to assess the functional significance of TMPRSS2 and CXCL10 in prostate cancer development." (PMID 36239108, 2022). "SCL45A3 is an androgen-regulated gene that, like TMPRSS2, is seen as a recurrent fusion partner with ERG in prostate cancer." (PMID 36337169, 2022). "Prostate cancer frequently harbors the chromosomal rearrangement of the E26 transformation-specific (ETS) gene, and the most frequent fusion partner gene is TMPRSS2." (PMID 36289913, 2022).